TIMP1 (TIMP metallopeptidase inhibitor 1)
Diseases named in the same sentence as TIMP1 in open-access papers (continued):
Sharing a sentence is not in itself a finding about the gene and the disease.
cancer (continued). "In this study, we find that TIMP1 is substantially up-regulated during tumorigenesis through analyzing cancer bioinformatics databases, which is further confirmed by IHC tissue microarrays of clinical samples." (PMID 35778451, 2022). "TIMP1 was primarily located in the membranes and cytoplasm of cancer cells and renal tubular epithelial cells." (PMID 35281807, 2022). "Currently, a number of studies have indicated TIMP1 is highly expressed in cancer cells and its high expression correlates with poor prognosis of patients." (PMID 35778451, 2022). "TIMP1 is a member of the tissue inhibitor of metalloproteinase (TIMP) family, which is prominently appreciated as natural inhibitors of cancer-promoting metalloproteinases." (PMID 35830566, 2022). "This prompted us to investigate if serum-derived EVs from cancer sera can recapitulate the upregulation of TIMP1 in recipient fibroblasts, promoting the ECM remodelling as a perquisite for the formation of a pre-metastatic niche." (PMID 35140332, 2022). "Tissue inhibitor of metalloproteinase-1 (TIMP-1) is a member of the TIMP family (TIMP-1 to -4) that is overexpressed in many cancers, including HNSCC." (PMID 36294681, 2022). "In the resectable cohort, RANTES, TIMP-1, FGF-4, and IL-10 individually differentiated patients according to their cancer-associated survival." (PMID 36497475, 2022). "TIMP1 is involved in a variety of pathological processes, including wound healing and cancer metastasis." (PMID 35719390, 2022). "After adipocytes are reprogrammed into cancer-associated adipocytes by an EOC-derived mediator, these activated adipocytes can release various adipokines, such as IL-6, IL-8, MCP-1, and TIMP-1 that contribute to building the omental metastatic niche for EOC." (PMID 35563509, 2022). "GO enrichment analysis of MMP9, TIMP1 revealed that these two genes are playing a significant role in metabolic, neurological, cardiovascular diseases and cancers." (PMID 35246549, 2022). "TIMP-1, overexpressed across almost all cancer types, is found to protect cells against chemotherapy-induced apoptosis." (PMID 35534592, 2022). "TIMP-1 has been reported to act in a growth-stimulatory manner on many cancer cells, including BC cells, and CD63 and ITGB1 were linked to drug resistance of BC cells." (PMID 36291767, 2022). "We then evaluated the prognostic value of TIMP1 and used PROGgeneV2 to investigate the potential correlations between TIMP1 level and survival outcome of cancer patients." (PMID 35778451, 2022). "In particular, several evidences reported the ability of TIMP-1 to protect cancer cells from apoptosis and induce epithelial-to-mesenchymal transition by binding its receptor CD63." (PMID 36140255, 2022). "In this study, we analyzed cancer databases and identified TIMP1 and six other genes to be potential markers for driving cancer progression in GBM patients." (PMID 35778451, 2022). "In contrast, TIMP-1, another of the differential markers shown here, is a soluble factor implicated in the reprogramming of SASP, again in the context of cancer, and it has been involved as a neuroprotective response in G93A mice." (PMID 35916061, 2022). "Cancer-associated death was significantly longer in subjects with low levels of RANTES, TIMP-1, and FGF-4 (p = 0.002, p = 0.014 and p = 0.028, respectively)." (PMID 36497475, 2022). "Despite MMP-9 overactivation, it has been shown that free TIMP-1 molecules also promote cancer growth." (PMID 34183752, 2021). "As TIMP-1 is only able to trigger intracellular signaling pathways and modulate cell behavior through its interaction with CD63 and β1-integrin, the formation of TIMP-1/CD63/β1-Integrin complex became an interesting target for cancer research." (PMID 34502227, 2021). "ITGB5, TIMP1, and TMEM176B can be used as molecular diagnostic targets or therapeutic targets in the future, as their combination is useful for cancer treatment." (PMID 34109215, 2021).
cancer (continued). "TIMP1, which is the first-discovered natural collagenase inhibitor, has been demonstrated to be related to the occurrence of a variety of cancers." (PMID 34775375, 2021). "Previous studies revealed a correlation between TIMP-1 expression and poor prognosis in cancer, and the structure-function interaction of TIMP-1 and CD63 has been demonstrated in live cells." (PMID 34611125, 2021). "The expression of TIMP-1 and -2, MMPs and cancer stem cells (CSCs) were upregulated in response to chemotherapy treatments in cancer cell lines." (PMID 35047406, 2021). "The overexpression of N-acetylglucosaminyltransferase V (MGAT5A), evidenced in CRC, promotes cancer cell migration and invasiveness through aberrant glycosylation of TIMP-1 (tissue inhibitor of metalloproteinase-1)." (PMID 34070747, 2021). "CD63, β1-integrin, and TIMP-1 are among glycoproteins already identified as targets for aberrant N-glycosylation in cancer." (PMID 34502227, 2021). "In contrast, many studies have shown that TIMP-1 expression is increased in several types of tumors, and this increase was correlated with a poor prognosis and lower survival in cancer patients." (PMID 34502227, 2021). "On the other hand, the expression level of TIMP1 in cancer cells treated with IKM5 was significantly higher than the control group, which is in line with our observations." (PMID 34011277, 2021). "Among the DEGs in myeloid cells, SPP1 and TIMP1 were the most significantly upregulated genes in hypoxia-high cells across cancers." (PMID 34676217, 2021). "Considering the intriguing dual role of TIMP1 in regulating pathways of cancer progression in a bi-phasic manner and recent evidence that TIMPs can function as alarmins, we examined the effects on ILCs as a focus for our current study." (PMID 34638439, 2021). "We found that, compared with normal tissues, the TIMP1 protein was expressed highly and significantly in cancer samples, while the ITLN1, TSPAN11, CPRC5B, and CXCL13 proteins were expressed poorly in cancer samples." (PMID 33579281, 2021). "The amount of TIMP-1 significantly decreased in high-grade cancer tissue but still it was higher in comparison to control." (PMID 32049862, 2020). "Clinical studies have shown that high expression of TIMP1 is positively correlated with a poor prognosis of colon, brain, prostate, breast, lung, and several other cancers." (PMID 32766727, 2020). "SNAIL leads to the induction of TIMP-3, and similarly, although independent of the metalloproteinase inhibitory function, the expression of TIMP-1 induces TWIST1 to negatively regulate E-cadherin in cancer cells, while TIMP2 upregulates this cadherin." (PMID 33419373, 2020). "While TIMP1 has been shown to be overexpressed in many malignant tumors, the prognostic value and potential function of TIMP1 in ccRCC is still unclear." (PMID 32420905, 2020). "Mechanistically, functional modifications of adhesion molecules (integrins and cadherins), matriptase, tissue inhibitor of metalloproteinase-1 (TIMP-1), and growth factor receptors by GnT-V have been reported to be involved in cancer malignancy." (PMID 31936666, 2020). "The role of TIMP-1 in cancer is controversial, because it can have both pro- and antitumoral effects." (PMID 33419373, 2020). "On the other hand, it has been reported that theincidence of cancer is increased when the actions of TIMP-1 and TIMP-2 are abnormal,and increased expression of TIMP-1 has been suggested to be a useful basis fordiagnosing of malignant tumors." (PMID 33152052, 2020). "In terms of their potential impact in cancer, it is known that EV-derived TIMP-1 binds to CD63 and β1 integrin, which induces survival signals and promotes metastatic niche formation." (PMID 32610589, 2020). "TIMP1 has been shown to be highly expressed in many types of cancer, consequently correlated to their poor prognosis." (PMID 32936304, 2020).
cancer (continued). "The lower plasma ratio in cancer patients is determined by the high TIMP-1 concentration and relatively low MMP-9 concentration in comparison to the control group." (PMID 31143300, 2019). "Circulating TIMP-1 in serum or urine has been regarded as a novel biomarker for the diagnosis and prognosis of various diseases, including cancer." (PMID 31443242, 2019). "We determined the possible activity of TIMP1 mRNA carried by platelets in stimulating cancer cells proliferation and apoptosis." (PMID 31639773, 2019). "Consistently, there was a significant negative correlation between hepatic cyclin D1 gene expression and cell death and a significant positive correlation between cyclin D1 expression and cancer metastatic capability (as assessed by the MMP-2:TIMP-1 ratio)." (PMID 31836811, 2019). "Incubation of cancer cells with platelets from CRC patients increased the levels of cellular TIMP1 protein, and this increase of TIMP1 protein was suppressed by co-transfection with the TIMP1 siRNA." (PMID 31639773, 2019). "TIMP-1 is associated, independently of its MMP-inhibitory function, with the induction of the EMT phenotype and mediates cancer-stellate cell interactions." (PMID 31200779, 2019). "Accordingly, one would expect TIMP‐1 to exert mainly a beneficial effect on cancer outcomes, by inhibiting remodeling of the ECM and therefore blocking invasion and metastasis." (PMID 31545548, 2019). "The platelets of CRC patients increased the TIMP1 protein level in cancer cells compared with platelets of HVs." (PMID 31639773, 2019). "Both RANTES and IL-8 are suggested to rather promote than reduce cancer cell invasion, so we focused on the further examination of TIMP1 and TIMP2." (PMID 31836008, 2019). "The analysis of TIMP-1 concentration in plasma revealed a significantly higher level in the case of poorly differentiated tumors than in G1 and G2 cancers." (PMID 31143300, 2019). "We also found that inhibition of TIMP-1 showed reduced cancer sphere formation and expression of CSC markers." (PMID 30486830, 2018). "We found that, compared with levels in healthy controls, only TIMP-1 levels were marginally elevated among the cancer patients." (PMID 29929486, 2018). "(a) Chemotherapy can induce endothelial cells to secrete IL6 and tissue inhibitor of metallopeptidase (TIMP1), creating an environment that increases cancer cell survival." (PMID 30373101, 2018). "One possible explanation is that TIMP-1 released by cancer cells during the prior 48-h cisplatin treatment more effectively blocks migration if HUVECs are immediately exposed to the total TIMP-1 content of CM prior to being subjected to the upper chamber." (PMID 30344920, 2018). "Upregulated expression of TIMP-1 is observed in various tumor tissues and is a significant indicator of cancer invasion, metastasis and survival of patients with cancers." (PMID 30458003, 2018). "The present study investigated the morphology as well as MMP and TIMP-1 levels in normal peritoneal tissue and peritoneum invaded by cancer cells, in samples taken during CRS for peritoneal carcinomatosis." (PMID 29623449, 2018). "In recent years, it has been also established that TIMP-1 has a role in epithelial to mesenchymal transition (EMT) premetastatic niche formation and interaction with cancer - associated fibroblasts." (PMID 29507665, 2018). "Recent studies have demonstrated a role for TIMP-1 in EMT, a feature associated with aggressive migratory cancer cells." (PMID 29507665, 2018). "Several studies have reported that TIMP1 played a role in anti-apoptosis by suppressing BAX in cancer cells and mouse bone marrow stromal cell line." (PMID 29742163, 2018). "Our findings shed light on a new ligand–microdomain transmembrane signal transduction platform on cell surface, and highlight dynamic cross-talk between extracellular fluid and cancer cells mediated by TIMP-1 and CD82." (PMID 28030805, 2017).
cancer (continued). "Proteins involved in cancer cell invasion, including TIMP-1, TIMP-2, and CD147, were expressed at increased levels after ANDR treatment." (PMID 28194420, 2017). "According to immunohistochemistry results of 32 patients in this study, we believe that defects in the N-terminus of TIMP-1 and CD82 endocytosis deficiency are both responsible for cancer development." (PMID 28030805, 2017). "CD82 directly binds to TIMP-1 N-terminal region through its large extracellular loop and co-localizes with TIMP-1 in both cancer cell lines and clinical samples." (PMID 28030805, 2017). "In fact, different authors have confirmed a positive correlation of high TIMP1 expression with a poor prognosis in lung, brain, prostate, breast, colon, and several other cancers." (PMID 28430130, 2017). "Tumor necrosis factor-α, VEGF and TIMP-1 are potent tumorigenic and angiogenic factors that contribute to cancer progression." (PMID 27028862, 2016). "The observation that TIMP-1 plays a pivotal role in this response is corroborated by several investigations that found a correlation between cancer cell invasion and decreased TIMP-1 levels." (PMID 26930716, 2016). "Tissue inhibitor of metalloproteinases-1 (TIMP-1) has been associated with poor prognosis and resistance towards chemotherapy in several cancer forms." (PMID 27619981, 2016). "TIMP1 was shown as a downstream target of NF-κB signaling in which TIMP1 induced by the activation of NF-κB signaling in cancer models or under UPR and ER stress." (PMID 27494843, 2016). "Positive staining of TIMP1 protein expression was observed mainly in the cytoplasm of the cancer cells." (PMID 27644693, 2016). "As an endogenous inhibitor of MMPs, TIMP-1 was found to repress cancer cell growth and invasion by inhibiting the activity of MMPs." (PMID 25909286, 2015). "It is reported that activation of both PI3K/Akt and ERK/MAPK pathways increases MMP2 and decreases TIMP1 expression in cancer cells." (PMID 25909166, 2015). "The areas under the receiver operating characteristic (ROC) curve for the cancer group were 0.821 for TIMP-1, 0.888 for COX-2, and 0.880 for MMP-7 (p = 0 < 0.001)." (PMID 29201696, 2015). "Together, these studies define TIMP-1 as an important cancer biomarker and demonstrate the potential TIMP-1 as a crucial therapeutic target." (PMID 26366732, 2015). "Silencing of TIMP-1 by promoter methylation is a feature of cancer cells, and treatment with demethylating agent AZA results in the induction of TIMP-1 in a number of cancer cell lines as well as endometrial stromal cells." (PMID 26691525, 2015). "TIMP-1 status was available from 264 of 337 patients and 210 (80%) of the tumors were classified as cancer cell TIMP-1 positive." (PMID 24884504, 2014). "Curcumin successfully down regulated the MMP-2, -9 and TIMP-1, -2 to maintain the net balance of MMPs/TIMPs to inhibit, at least in part, cancer cell invasion and migration in HT1080 human fibrosarcoma cancer cells." (PMID 25566531, 2014). "That LLC-associated increases in plasma concentrations of inflammatory cytokines PAI-1, MCP-1, TNF-α, protease uPA and angiogenic factors VEGF, TIMP-1 indicate the aggressiveness of this carcinoma model." (PMID 25356654, 2014). "Higher EGFR and TIMP1 were observed more frequently in the carcinomas of upper thoracic segment esophagus (P = 0.032; 0.00046)." (PMID 25337715, 2014). "Each MMP was detected at significantly higher rate in urine from cancer patients compared to control subjects except in MMP-9/TIMP-1 and ADAMTS-7." (PMID 23672427, 2013). "Up to now, however, the role of TIMP-1 as a predictive factor has been confirmed only in the case of cancer of the esophagus and the stomach." (PMID 23768069, 2013). "Positive staining was observed for TIMP-1 protein in the cytoplasm in the healthy mucosa adjacent to the cancer cells." (PMID 24137341, 2013).
cancer (continued). "Taken together, these results indicated that TIMP-1 not only serves as a prognostic marker for multiple cancer progression but also promotes the cancer progression." (PMID 24143225, 2013). "Together, our results establish the novel promotive effects of TIMP-1 on the cancer progression and CAF accumulation, the potential of TIMP-1 as a novel cancer therapeutic target, and the mechanism underlying the TIMP-1 effects." (PMID 24143225, 2013). "Taken together, the present study provides a new molecular insight into the novel oncogenic activity of TIMP-1 during cancer progression." (PMID 22701711, 2012). "In another study, the same group demonstrated that in human cancer cell lines increased expression of TIMP-1 mediates an anti-invasive effect of cannabinoids." (PMID 23202950, 2012). "A disintegrin and metalloproteinase-10, a sheddase of HER2/neu, can drive cancer progression and its activity is inhibited by tissue inhibitor of metalloproteinase-1 (TIMP-1)." (PMID 22339939, 2012). "Until recently TIMP-1 and HIF-1α (and in consequence miR-210) were seemingly totally un-related factors whose elevation is associated with bad prognosis for cancer patients." (PMID 22807917, 2012). "Some previous studies also found TIMP-1 up-regulation by activated p38 MAPK in human cancer cells treated with chemotherapeutic agents cannabidiol and cisplatin, which exhibit potent inhibition on human cancer cell invasion in vitro." (PMID 23029478, 2012). "Among MMPs and TIMPs, TIMP-1 is frequently overexpressed and shown to serve as a prognostic marker in several types of human cancers including breast cancer, prostate cancer, lung cancer, melanoma, multiple myeloma, and glioblastoma." (PMID 22701711, 2012). "Due to the importance of TIMP-1 in cancer cells invasion, and angiogenesis, we have demonstrated that 3-azidoWA treatment augmented the expression of TIMP-1 which is a modulator of MMP-2 expression in both cell lines, in dose dependent manner." (PMID 22962598, 2012). "TIMP-1 is frequently overexpressed in several types of human cancers and serves as a prognostic marker." (PMID 22701711, 2012). "ProMMP-1 was significantly increased (p = 0.04) compared to cancer control tissue and TIMP-1 was significantly higher than all other groups (p<0.04 all comparisons) in fibrotic CD muscle." (PMID 23300643, 2012). "TIMP-1 is one of four natural inhibitors of the matrix metalloproteinases (MMPs), the proteolytic enzymes that play an important role in cancer dissemination." (PMID 22988515, 2012). "Firstly, several studies indicated that TIMP-1 can stimulate cancer proliferation independent on its MMP-inhibitory function." (PMID 22988515, 2012). "Clinical findings support the potential use of TIMP-1 as a predictive biomarker for patient therapeutic response and cancer survival." (PMID 22957045, 2012). "TIMP-1 plays an important role in regulation of extracellular matrix remodelling, which is one of the processes involved in cancer growth and spread." (PMID 22933958, 2011). "Patients and controls did not have significant differences in their serum MMP-9 and TIMP-1 levels, although the ranges for MMP-9 and TIMP-1 concentrations were wider in cancer patients compared with healthy controls." (PMID 20671952, 2010). "The most prominent cytokines that have also been shown to be linked with cancer development were IL-6, IL-8 (CXCL8), GRO/GRO-α (CXCL1), GCP-2 (CXCL6), and TIMP-1." (PMID 20723242, 2010). "Specimen 08-032 showed minimal reactivity for TIMP1, indicating a relatively pure sample with little contamination by non-cancer." (PMID 20021671, 2009). "For instance, a number of studies have shown that increased serum concentrations of tissue inhibitor of metalloproteinases 1 (TIMP-1), a major inhibitor of metalloproteinases, often is associated with a poor clinical outcome in various cancer forms." (PMID 19384300, 2009).